CAT (catalase)
Diseases named in the same sentence as CAT in open-access papers (continued):
Sharing a sentence is not in itself a finding about the gene and the disease.
mastitis (15 papers, 2014 to 2025). Inflammation of breast tissue during lactation or postpartum due to an obstructed duct or infection. "Muralidhar reported an increase in MDA levels and SOD and catalase (CAT) activity in mice with mastitis induced by Staphylococcus aureus, whereas nanosilver treatment significantly reduced the bacterial load and SOD and CAT activity in breast tissue." (PMID 40266913, 2025). "In this context, young scientists from the Orel State Agrarian University studied catalase activity (“permanganometric” method) in the milk of cows with clinical and subclinical mastitis." (PMID 41283399, 2025). "This study confirms that catalase activity increases sharply (by almost 10-fold) in the milk of cows not only with mastitis but also with its subclinical form." (PMID 41283399, 2025). "Mastitis-affected sheep had significantly reduced expression levels of the genes CAT, GPX1, ATOX1, GST, and Nrf2 compared to resistant ewes." (PMID 40542007, 2025). "In the present study, a real-time PCR was carried out to quantify the mRNA level of SELL, ABCG2, SLC11A1, FEZL, SOD1, CAT, GPX1, and AhpC/TSA genes in tolerant and susceptible Holstein and Brown Swiss dairy cows to mastitis." (PMID 35737346, 2022). "As far as we are concerned, this is the first study revealing SNPs in SELL, ABCG2, SLC11A1, FEZL, SOD1, CAT, GPX1, and AhpC/TSA genes as candidates for mastitis tolerance/susceptibility in Holstein and Brown Swiss dairy cows." (PMID 35737346, 2022). "PCR-DNA sequencing of SELL, ABCG2, SLC11A1, FEZL, SOD1, CAT, GPX1, and AhpC/TSA revealed nucleotide sequence variations in the form of SNPs associated with mastitis tolerance/susceptibility in investigated Holstein and Brown Swiss dairy cows." (PMID 35737346, 2022). "Early evidence indicated that HM of mothers with mastitis showed a higher content of minerals, chlorides, and catalase activity, and lower levels of lactose, fat, total proteins, and total casein fractions, in comparison with HM from healthy women." (PMID 33117843, 2020). "Furthermore, when compared with the model group, treatment with Rg1 or rosiglitazone significantly decreased the levels of MDA, while increasing SOD and CAT in LTA-induced mastitis mice." (PMID 39765775, 2024). "Consequently, the aim of the current work was to revealing the association of SNPs and expression profile of SELL, ABCG2, SLC11A1, FEZL,SOD1,CAT,GPX1, and AhpC/TSA genes with mastitis tolerance/susceptibility in Holstein and Brown Swiss dairy cows." (PMID 35737346, 2022). "as well as on other gram-positive, catalase-negative cocci associated with bovine mastitis, reliable and robust identification techniques are of utmost importance and urgent need." (PMID 25015262, 2014). "In this study, the activities of SOD, CAT, GSH, GPx, and GST significantly decreased (p < 0.01) in the blood of mastitis-induced mice, indicating oxidative stress, which is consistent with the findings of Chinchali and Kaliwal." (PMID 40098888, 2025). "Consequently, SELL, ABCG2, SLC11A1, FEZL, SOD1, CAT, GPX1, and AhpC/TSA regulation mechanisms are well understood in the mastitis tolerant and affected Holstein and Brown Swiss dairy cows." (PMID 35737346, 2022). "We therefore assessed the potential of FTIR spectroscopy and MALDI-TOF MS for identification and differentiation of mastitis relevant gram-positive, catalase-negative cocci." (PMID 25015262, 2014). "In the present study, the potential of FTIR spectroscopy and MALDI-TOF MS for identification and differentiation of mastitis relevant streptococci and other gram-positive, catalase-negative cocci was assessed and the applicability of both methods for routine diagnosis was examined in a blind study." (PMID 25015262, 2014).
mastitis (continued). "In the current investigation, qRT-PCR was used to measure the levels of antioxidant (CAT, GPX1, Keap1, OXSR1, ATOX1, GST, and Nrf2) and immune (IFN-γ, IL-4, TNF-α, MYD88, CCL5, TLR4, TLR9, LTF, and PRLR) genes in Barki ewes that were resistant and non-resistant to mastitis." (PMID 40542007, 2025).
migraine (15 papers, 2019 to 2026). "The higher frequency of SOD and CAT polymorphisms in individuals suffering from migraine results in decreased antioxidant protection." (PMID 38674218, 2024). "Decreased activity of catalase, an enzyme that deactivates hydrogen peroxide, has been demonstrated in the serum of patients with a family history of migraine, suggesting that migraine may be causally linked to disturbances in the antioxidant system." (PMID 40724883, 2025). "Association analysis of the CAT rs1001179 variant with migraine triggers." (PMID 36698892, 2022). "In addition, homozygosity for the variant T allele of the CAT rs1001179 seems to be associated with sleep and weather changes as triggering factors inducing migraine attacks." (PMID 36698892, 2022). "Lastly, variability in the CAT, GSTP1 and UCP2 genes were associated with sleep/weather changes, alcohol consumption and physical exercise, respectively, as migraine triggers." (PMID 36698892, 2022). "As in our study, the catalase level, as a contributor to the antioxidant system, was reported to be significantly decreased in migraine patients." (PMID 32516927, 2020). "Paw mechanical thresholds, migraine-like behaviors (head-face scratching, body grooming, exploration, and freezing time), and oxidative markers (malondialdehyde, catalase, reduced glutathione, and superoxide dismutase) in the trigeminal nucleus caudalis were assessed." (PMID 41919512, 2026). "In this context, it is interesting to ask whether the prevalence of migraine is higher in patients with other syndromes characterized by catalase dysfunction." (PMID 40724883, 2025). "Togha, Mansoureh, using colorimetric and photometric methods, found significantly increased levels of malondialdehyde and nitric oxide and significantly decreased activities of catalase and superoxide dismutase in the plasma of migraine patients, indicating increased oxidative stress." (PMID 39850553, 2024). "A polymorphism in the SOD2 gene was associated with unilateral cranial autonomic symptoms in migraine with aura patients, and in paediatric migraine patients’ polymorphisms in the SOD2 and catalase gene were significantly higher in both migraine with and without aura patients compared to controls." (PMID 30974836, 2019). "CAT was significantly lower and MDA concentration was significantly higher in the migraine group compared to the control group." (PMID 39416954, 2024). "A different pattern of oxidative stress parameters was observed between groups with significantly higher values of NOx, MDA, and TOS, and, respectively, significantly lower values of catalase and TAC among the migraine group as compared to the control group." (PMID 32516927, 2020). "A significant positive correlation between catalase and macular RNFL thickness (inner ring, temporal quadrant) in migraine patients, for both eyes, was observed (p = 0.014 for the right eye and p = 0.12 for the left eye)." (PMID 32516927, 2020). "All of the parameters that reflect the oxidant/anti-oxidant balance in our study (NOx, MDA, TOS, catalase, and TAC) were found to be significantly modified in migraine patients compared with the control group." (PMID 32516927, 2020). "Patients with RRMS who did not experience migraine exhibited lower levels of SOD, CAT, and GSH-Px compared to their healthy counterparts." (PMID 38674218, 2024). "Additionally, our findings regarding lower serum total non-enzymatic antioxidant capacity, CAT, and SOD levels in migraineurs than controls are partially in accordance with the findings of a meta-analysis on the association between oxidative/nitrosative pathways in migraine." (PMID 31837702, 2019). "Comorbidity between MS and migraine could increase the risk of finding not only low values of vitamin D and VITDR but also a change in oxidative stress markers (such as SOD, CAT, GSH-Px, and TAS) with respect to MS patients without migraine." (PMID 39860566, 2025).
migraine (continued). "In addition, the SOD, CAT, GSH-Px, and TAS values were lower in pwMS with migraine than in pwMS without migraine (all p < 0.001)." (PMID 39860566, 2025). "Moreover, the values of SOD, CAT, and GSH-Px in the patients with RRMS who experienced migraine were significantly lower than those in the patients without migraine." (PMID 38674218, 2024). "Additionally, the study found that migraine patients with WHM-type lesions were characterized by lower CAT activity and elevated MDA concentration in comparison with migraine patients without WHM-type lesions." (PMID 32012936, 2020).
myocardial ischemia (15 papers, 2011 to 2025). A disorder of cardiac function caused by insufficient blood flow to the muscle tissue of the heart. "Furthermore, another recent research has demonstrated that SETD7 can methylate Yes-associated protein (YAP) during myocardial ischemia, promoting its retention in the cytosol and diminishing the transcription of antioxidant genes such as manganese superoxide dismutase (MnSOD) and catalase (CAT)." (PMID 41371168, 2025). "This is in agreement with the findings of a previous study which reported that hesperidin significantly improved SOD and catalase enzyme activity in rats with myocardial ischemia." (PMID 37082190, 2023). "Effects of formononetin-7-O-β-(6′′-O-succinyl)-D-glucoside (FMP) on SOD, LDH and CAT activities in serum of mice with myocardial ischemia (x ̄±s, n = 10)." (PMID 34970243, 2021). "The activation of PPARα protects myocardial cells by increased expression and activation of superoxide dismutase (SOD1, SOD2) and catalase and suppresses the generation of ROS in myocardial ischemia." (PMID 30911353, 2019). "EGb 761 also restrained the oxidative stress related to myocardial ischemia injury as evidenced by decreased malondialdehyde, superoxide dismutase, catalase, glutathione-peroxidase, glutathione reductase activity." (PMID 29156826, 2017). "Our results suggest the involvement of hyperhomocysteinaemia in the drop of erythrocyte catalase activity related to myocardial ischemia reperfusion." (PMID 23631751, 2013). "The results of the current study suggest that decreased SOD and catalase levels might be due to increased utilization to trap the free radicals induced by myocardial ischemia." (PMID 34177373, 2021). "In one study administration of apricot kernel oil increased CAT, GPx, and SOD myocardial activities, whereas decreased MDA level in myocardial ischemia–reperfusion in a rat model." (PMID 39170485, 2024). "The greater protective effects of combined use of PEP-1-SOD1 and PEP-1-CAT against myocardial ischemia-reperfusion injury are due to the combined function of SOD1 and CAT." (PMID 21600015, 2011). "In addition, the extract of Hibiscus rosa-sinensis, another flower of the Malvaceae family, significantly raised GSH levels and SOD and CAT activities and decreased LPO in myocardial ischemia/reperfusion in rats." (PMID 31049126, 2019). "Summarily, dioscin ameliorates myocardial ischemia/reperfusion injury through suppressing reactive oxygen species via downregulation of Nox2 and upregulation of the antioxidative enzyme, including SOD, CAT, GPx, and GSH, leading to alleviate cardiac dysfunction." (PMID 34664015, 2021).
oral cancer (15 papers, 2014 to 2025). "Therefore, our results suggest that oral cancer cell death is linked to cellular free radical production and the downregulation of catalase protein expression under 26G and 36M treatments." (PMID 37372967, 2023). "Endothelin-1 represents a potential biomarker for the development of OSCC in patients with oral lichen planus and IL-8, IL-1β, glycoprotein M2BP (Mac-2 binding protein), CD59, myeloid protein 14 (MRP14) and catalase as salivary biomarkers of oral cancer." (PMID 36412636, 2022). "Pomegranate extract also downregulates NFE2L2, TXN, CAT, SOD1, and HMOX1 gene expressions in oral cancer cells and induces oxidative stress." (PMID 36139851, 2022). "Accordingly, the gene expressions of antioxidant genes such as NFE2L2, SOD1, TXN, GSR, CAT, and GPX1 were evaluated by qRT-PCR following UVC and/or sinularin treatments in oral cancer cells (Ca9-22 and CAL 27)." (PMID 34070049, 2021). "Similar to the present study, the mRNA expressions for several antioxidant genes (NFE2L2, GCLC, TXN, CAT, SOD1, HMOX1, and NQO1) were downregulated at 24 h POMx for three oral cancer cell lines." (PMID 34356350, 2021). "Accordingly, the antioxidant signaling gene expression for mRNA, including NFE2L2, GCLC, TXN, CAT, SOD1, HMOX1, and NQO1, was examined for POMx-incubated oral cancer cells." (PMID 34356350, 2021). "In the present study, EANT generates oxidative stress, which is accompanied by mRNA overexpression for antioxidant genes (NFE2L2, CAT, HMOX1, and TXN) in oral cancer cells." (PMID 34575651, 2021). "In the current study, antioxidant gene expressions (NFE2L2, SOD1, TXN, GSR, CAT, and GPX1) in oral cancer Ca9-22 and CAL 27 cells were highly downregulated by UVC/sinularin combined treatments compared to the separate treatments." (PMID 34070049, 2021). "In response to oxidative stresses, the mRNA for antioxidant signaling, such as nuclear factor erythroid 2-like 2 (NFE2L2), catalase (CAT), heme oxygenase 1 (HMOX1), and thioredoxin (TXN), are overexpressed in oral cancer cells." (PMID 34575651, 2021). "They found that the risk of oral cancer development in smokers was significantly higher than non-smokers on the basis of erythrocytic glutathione reductase (GR), SOD, catalase (CAT) and plasma thiol." (PMID 31582940, 2019). "ANE-induced cytotoxicity was inhibited by catalase and enhanced by dicoumarol, suggesting that AN components may contribute to the pathogenesis of OSF and oral cancer via induction of aberrant differentiation, cytotoxicity, COX-2 expression, and PGE2/PGF2αproduction." (PMID 25051199, 2014).
renal fibrosis (15 papers, 2012 to 2025). A final common manifestation of a wide variety of chronic kidney diseases characterized by glomerulosclerosis and tubulointerstitial fibrosis. "Mice deficient in catalase were shown to have more severe renal fibrosis after UUO indicating the importance of oxidants in the pathogenesis of UUO." (PMID 31479481, 2019). "A recent study reported that the loss of catalase-buffering capacity leads to an increase in oxidative products and more severe renal fibrosis, resulting in progressive kidney disease in catalase-deficient mice." (PMID 24058721, 2013). "The catalase-deficient mice are more susceptible to oxidant tissue injury and renal fibrosis." (PMID 22844329, 2012). "In the LPS-induced renal fibrosis, increased MDA levels and decreased total thiol groups as well as decreased SOD and CAT activities were identified." (PMID 38911247, 2024). "Our data demonstrated that CO decreased inflammation, oxidative stress and renal fibrosis, as evidenced by quantifying the expression of TNF-α, IL-10, CAT, SOD, α-SMA and TGF-β." (PMID 37447251, 2023). "In doxorubicin-induced renal fibrosis models, BBR reduces collagen deposition and apoptosis by inhibiting the NF-κB/TGF-β1 signaling pathway and increasing antioxidant enzymes’ efficacy, including SOD and CAT." (PMID 40567371, 2025). "Further study found that, in a mouse model of unilateral ureteral obstruction, H2S could alleviate the oxidative stress by upregulating catalase (CAT), Superoxide dismutase (SOD), and glutathione (GSH), thereby improving renal fibrosis." (PMID 26823949, 2016). "Gallic acid can protect against GX-induced renal fibrosis; Another research showed that the activities of both SOD and catalase were not significantly different after treatment with GX, though they were significantly increased by melthyglyoxal in human skin fibroblasts." (PMID 34922451, 2021).
alcohol (14 papers, 2012 to 2025). "As has been shown, a common polymorphism in the promoter region of the catalase gene, CAT c.-262C > T, has an impact on alcohol dependence and its severity." (PMID 33924016, 2021). "CAT is also widely expressed in the brain and a number of studies suggest that polymorphisms in the CAT gene are involved in the level of response to ethanol and alcohol dependence (AD) and abuse." (PMID 37098020, 2023). "The role of catalase in alcohol use disorder is supported by the results of a study showing that subjects with a family history of alcoholism have a higher catalase activity than a control group." (PMID 33924016, 2021). "However, some findings indicate that CAT activity might also be reduced in patients with alcohol dependence." (PMID 39352642, 2024). "Research has demonstrated that alcohol can reduce the overall antioxidant activity in the serum of individuals with alcohol dependence and impair the functions of critical antioxidant enzymes such as superoxide dismutase (SOD), catalase (CAT), and glutathione peroxidases (GPX)." (PMID 39352642, 2024). "Also in a prior study, supplementation with BCAAs in-creased the mRNA levels of glutathione peroxidase 1 (GPX1), catalase, and SOD in the liver tissue of alcohol-induced rats." (PMID 38111317, 2024). "Moreover, alcohol induced excessive oxidative stress, as evidenced by an increase of the malondialdehyde level and reactive oxygen species production, while reducing antioxidant enzymes (T‐SOD, CAT, and GPx) in liver, were inhibited by administration of LBPs." (PMID 33312537, 2020). "However, the internal anti-oxidative system including SOD and CAT in the context of ALD are not activated, indicating that JGB does not protect the liver from alcohol-induced injury by alleviating oxidative stress." (PMID 29414910, 2018).